APOE (apolipoprotein E)
Diseases named in the same sentence as APOE in open-access papers (continued):
Sharing a sentence is not in itself a finding about the gene and the disease.
atherosclerosis (continued). "The development of atherosclerosis is confirmed by Oil Red O staining and the significant increase in the levels of iron and ferritin was demonstrated by direct measurement of total iron content and also by western blot and RT-PCR analysis in the aortic tissues of ApoE–/– mice." (PMID 35669479, 2022). "As found by Stepankova: compared to ApoE−/− mice raised under conventional conditions, GF ApoE−/− mice consuming the same low-cholesterol standard diet instead developed atherosclerotic plaques, suggesting that gut microbiome can protect mice from atherosclerosis." (PMID 36439791, 2022). "In apolipoprotein E-deficient mice, evodiamine significantly reduced atherosclerosis, hyperlipidemia, and systemic inflammation and this beneficially therapeutic effect was not seen in ApoE−/− mice that lack TRPV1, suggesting that TRPV1 curbs the development of atherosclerosis." (PMID 36589466, 2022). "ApoE may provide novel therapeutic targets for the treatment of atherosclerosis." (PMID 36035124, 2022). "Regardless, both B-1a and B-1b cells are largely considered beneficial in atherosclerosis through their secretion of natural, relatively unmutated IgM directed against OSEs, which aid in the attenuation of plaque development in atherosclerotic ApoE−/− mice by blocking foam cell development." (PMID 36461105, 2022). "Therefore, in this study, we investigated the protection role and molecular mechanisms of homoplantaginin and its derivative dihydrohomoplantagin in the process of atherosclerosis, using a model of endothelial cell injury induced by oxLDL in vitro and apoE-/- atherosclerotic mice model in vivo." (PMID 35335352, 2022). "In apolipoprotein E-deficient mice model, CCL4 antibody treatment reduced circulating IL-6 and TNF-α whereby the authors concluded that CCL4 inhibition seems to be a promising tool within the box of anti-inflammatory therapeutics in patients diagnosed with atherosclerosis." (PMID 36290379, 2022). "A putative mechanistic link between APOE and FTO is underscored by studies showing that overexpression of FTO in APOE-deficient mice reduces cholesterol and inflammatory cytokine synthesis by macrophages and alleviates atherosclerosis associated with the absence of APOE." (PMID 35454109, 2022). "Firstly, we performed the study using double-knockout mouse model to describe the metagenome signature of PSRC1 deletion in the context of atherosclerosis; however, the response may not exclude the pro-inflammatory environment induced by apoE deficiency." (PMID 35613310, 2022). "Similarly, SGLT2i and acarbose demonstrated effects beyond their glucose‐lowering potential by lowering the incidence of atherosclerosis in diabetic ApoE −/− mice with the former, and that of lung tumors, liver degeneration, and glomerulosclerosis with the latter." (PMID 35343051, 2022). "Therefore, we proposed that endurance exercise could alleviate the atherosclerosis induced by a WD and genetic deletion of apolipoprotein E (ApoE) through modulation of the microbiota and its associated metabolites." (PMID 35256637, 2022). "Additionally, both of them restricted atherosclerosis development of apoE-/- mice." (PMID 35335352, 2022). "Importantly, a switch to apoptosis, which is non-lytic and non-inflammatory (in contrast to pyroptosis), will limit plaque progression, inflammation, and destabilization and thus, is regarded to be atheroprotective at this stage of atherosclerosis in ApoE−/− mice." (PMID 35625908, 2022).
atherosclerosis (continued). "Thus, if HDL is high, but cannot contribute to RCT for whatever reason, it may actually become an atherosclerosis-promoting lipoprotein, as evidenced by more severe atherosclerosis in apoE/SR-BI double knockout vs. apoE knockout mice." (PMID 35052806, 2022). "Further lncRNA-FA2H-2 knockdown experiments in ApoE-deficient mice showed that the size of plaques was enlarged and the cell death was enhanced, followed by an increased level of MLKL protein, suggesting the protective effect of lncRNA-FA2H-2 in atherosclerosis." (PMID 35548442, 2022). "Similarly, using Au-HDL nanoparticles, the assessment of plaques by CT and spectral CT was investigated as a means of characterizing the macrophage burden, calcification and plaque stenosis in an apolipoprotein E knockout (apo E-KO) mouse model of atherosclerosis." (PMID 35328130, 2022). "In addition, TLR4 knockdown significantly down-regulates early atherosclerosis in diabetic ApoE−/− mice, which may be related to monocyte activation that is mediated by the TLR4 signaling pathway." (PMID 35062863, 2022). "Our study also revealed that the infection of ApoE knock-out mice by P. gingivalis was induced efficiently in collaboration with Western diet, and the vaccination effect was comparable with that of pitavastatin in the prevention of atherosclerosis against the infection." (PMID 33976982, 2021). "Moreover, in diabetic ApoE null mice, PKCβ is involved in diabetes-accelerated atherosclerosis via regulation of the IL-18/IL-18BP and MAP kinase signaling pathways and promotes VCAM-1 expression, macrophage adhesion, EC dysfunction, aorta and macrophage inflammatory responses." (PMID 34276388, 2021). "The importance of T cell activation in atherosclerosis was demonstrated because ApoE knockout and immunodeficient (severe combined immunodeficiency mice without functional B and T lymphocytes) mice had less atherosclerotic lesions than ApoE knockout mice alone." (PMID 33834043, 2021). "Thus, ApoE KO is a commonly used animal model in atherosclerosis research." (PMID 34206159, 2021). "ApoE Kyoto may induce LPG while protecting against atherosclerosis." (PMID 33663537, 2021). "Compared to wildtype mice, ApoE mice on a normal chow diet have increased aortic expression of many antioxidant enzymes, including GPx1, GPx3, GPx4 and Txnrd prior to the development of atherosclerosis, but during lesion development, the expression of these antioxidant enzymes declines." (PMID 34579115, 2021). "Therefore, the high-fat diet-fed ApoE−/− mouse model is ideal for studying atherosclerosis." (PMID 34867337, 2021). "Additionally, to investigate whether SM is an effective therapeutic agent for CKD-mediated atherosclerosis, we assessed the effect of SM on atherosclerotic lesions in 5/6 Nx ApoE–/– mice." (PMID 34679653, 2021). "Therefore, the aim of the present study was to assess whether LOE improves endothelial dysfunction and prevents the development of atherosclerosis by reducing vascular ROS generation in an experimental model of atherosclerosis, the apoE−/− mice." (PMID 34834858, 2021). "We found in apolipoprotein E-deficient mice that lack of both the IL-18 receptor and the sodium-chloride co-transporter could limit atherosclerosis lesion development, but not single deficiency of either protein." (PMID 33924019, 2021). "Beyond its use in acute and chronic heart failure patients, Ivabradine may be effective in other inflammatory cardiovascular diseases such as atherosclerosis, as others recently found a significant improvement by early administration of Ivabradine in apoE-null mice." (PMID 33809359, 2021).
atherosclerosis (continued). "The section clearly showed the formation of extensive and typical atherosclerotic plaques in the carotid arteries of ApoE-/- mouse, which reflects the presence of lipid content in the atherosclerotic plaques in ApoE-/- mouse and provide the basis for the early diagnosis of atherosclerosis." (PMID 33777911, 2021). "However, this phenotype was absent in ApoE-/- Aid-/- mice, which shows that atherosclerosis itself was associated with local B cell expansion." (PMID 34305930, 2021). "Moreover, similar lesion distribution and progression as those in humans could be observed in ApoE−/− mice, making them a particularly popular animal model in atherosclerosis studies." (PMID 33413490, 2021). "Moreover, treatment with a low dose of THC could reduce the progression of atherosclerosis in apolipoprotein E knockout mouse model." (PMID 34500744, 2021). "In the diabetic mouse model, exosomes derived from VSMCs containing miR-221/222 were more likely to cause atherosclerosis compared with the non-diabetic mice, and the introduction of exosomes of diabetic VSMCs into ApoE-/- mice led to deterioration of atherosclerotic lesions." (PMID 34513963, 2021). "Importantly, injection of Lv‐miR‐195‐3p into ApoE−/− mice could alleviate the pathological process of atherosclerosis through the inhibition of pro‐inflammatory cytokines production." (PMID 34592792, 2021). "Additionally, atheroprone flow induces the nod-like receptor protein-3 (NLRP3) inflammasome in the endothelium through SREBP2, and the activated NLRP3 inflammasome synergizes with hyperlipidemia to increase atherosclerosis in apolipoprotein E-/- (ApoE-/-) mice." (PMID 34094640, 2021). "In addition, gene therapy with the CgC-derived peptide secretoneurin ameliorates hind limb and myocardial ischemia without influencing systemic atherosclerosis in apolipoprotein E-deficient mice." (PMID 34204153, 2021). "It indicated that feeding ApoE−/− mice with HFD could successfully replicate atherosclerosis model." (PMID 34305600, 2021). "To further verify that 3‐HB attenuates atherosclerosis in vivo via macrophages with high expression of Gpr109a, we generated two bone marrow chimeric mouse models by transplanting bone marrows from WT or Gpr109a−/− mice to lethal dose irradiation‐treated apoE−/− mice, respectively." (PMID 33977048, 2021). "In our study, we found that ApoE−/− mice fed with western‐type diet not only induced atherosclerosis but also stimulated adipose inflammation characterized by increased CLS formation, which suggested inflammation of WAT may accompany with and aggravate the process of atherosclerosis." (PMID 34528389, 2021). "Therefore, in view of the promising results previously obtained, the purpose of the current study was to assess the influence of anchovy viscera protein hydrolysates in reducing atherosclerosis in ApoE−/− mice used in previous studies through histological and immunohistochemical methods." (PMID 34206655, 2021). "Importantly, ApoE-ε4 is a well-known genetic risk factor for atherosclerosis and AD in the brain, unlike ApoE-ε2 and ApoE-ε3." (PMID 35822056, 2021). "Therefore, the ApoE knockout (ApoE−/−) model is used here to investigate low-dose IR effects in a situation of inflammation and persistent hyperactivity of the immune system along with hypercholesterinemia and atherosclerosis." (PMID 34831473, 2021). "Comparing wild-type VSMCs from an ApoE model of atherosclerosis with a flox’d Pink1 knockout of inducible mitochondrial dysfunction we show WT Pink1 is essential for normal cell viability, while Klotho mediates energetic switching which may preserve cell survival." (PMID 35008643, 2021). "These technical limitations might have contributed to the inability to detect any apoptotic changes in the aortic arch of apoE−/− mice treated with low dose radiation, which is considered to protect against atherosclerosis, when using 99mTC-labeled AnxA5 for autoradiographic analysis." (PMID 33810523, 2021).
atherosclerosis (continued). "In addition, Apolipoprotein E (ApoE)-deficient mice deficient in FABP4 exerted protective effects on atherosclerosis without affecting serum lipids or insulin sensitivity." (PMID 33287461, 2020). "Stem-loop qRT-PCR detected that the miR-124 expression level in the thoracic aorta tissues was downregulated in ApoE-/- C57B/L6J mice compared with that in the control mice, suggesting that the expression of miR-124 was negatively correlated with the p38 level during atherosclerosis development." (PMID 32611832, 2020). "Dementia may be a consequence of underlying atherosclerosis or could be independent of atherosclerosis as a convergent disease process sharing major pathophysiological elements, such as cholesterol, inflammation, and Apolipoprotein E polymorphism." (PMID 32925051, 2020). "Besides, our team also confirmed inhibition of ceramide synthesis could reduce lipid deposition and inflammatory response in vascular wall of ApoE-/-mice so as to delay progression of atherosclerosis." (PMID 32830858, 2020). "Furthermore, studies in apoE−/− mice suggest that T cells reactive to mCRAMP are functionally active in atherosclerosis and may be involved in modulating plaque calcification." (PMID 33123157, 2020). "Therefore, we analyzed the expression of PTPN2 in APOE-/- mice model of atherosclerosis." (PMID 33411686, 2020). "However, our present study has a limitation that CD137 and ApoE dual gene knockout mice should be applied to validate the proapoptotic effect of CD137 signaling in vivo to fully define the role of CD137 signaling in atherosclerosis." (PMID 32587470, 2020). "In this context the current study will test the hypothesis that administration of native human HDL will inhibit recombinant SAA’s propensity to elicit pro-inflammatory activity, stimulate oxidative damage, and enhance aortic and renal pathology in ApoE−/− mice mouse model of atherosclerosis." (PMID 32075280, 2020). "However, APOE also likely prevents atherosclerosis in part through its anti-inflammatory effects." (PMID 32849290, 2020). "Thus, mitochondrial fusion cleavage proteins may promote the development of atherosclerosis in ApoE−/− mice via inhibiting the PI3K/Akt/Bad signaling pathway and regulating apoptosis in vascular endothelial cells." (PMID 32685460, 2020). "However, circulating apoE, a glycoprotein involved in lipid transport and metabolism, may play a protective role in the development of atherosclerosis and CVD in humans." (PMID 33297350, 2020). "Furthermore, the in vivo viral overexpression in high-fat fed ApoE-/- mice (a murine model of atherosclerosis) showed that GRP119 has a protective effect against atherosclerosis via increasing the cholesterol efflux and reducing the proinflammatory cytokine expression." (PMID 32664594, 2020). "Moreover, apoE-/- mice are frequently used for testing potential therapeutic agents and environmental factors that may affect atherosclerosis development." (PMID 32428130, 2020). "Indeed, the endothelial cell P2Y1 receptor strongly contributes to leukocyte recruitment and exposure of adhesion molecules (P-selectin, ICAM-1, and VCAM-1) during inflammation, and P2Y1−/−/ApoE−/− mice showed reduced macrophage infiltration and atherosclerosis lesions." (PMID 33371312, 2020). "Therefore, GSNOR−/− apolipoprotein E (ApoE)−/− double knockout mice subjected to HHcy challenge exhibited much less T-cell activation and a significantly mitigated amount of total lesions of HHcy-induced atherosclerosis compared with GSNOR+/+ApoE−/− mice." (PMID 33126514, 2020). "Lack of FABP4 protects ApoE-deficient mice against atherosclerosis." (PMID 33287461, 2020). "In this study, we first confirmed the potent anti-atherogenic efficacy of Tan IIA using ApoE-/- mice—a well-established murine atherosclerosis model and then further investigated whether and how Tan IIA inhibits oxLDL-induced NLRP3 inflammasome activation in macrophages." (PMID 33290264, 2020).
atherosclerosis (continued). "Moreover, atherosclerosis is ameliorated by systemic TRAIL delivery in apoE‒/‒ mice." (PMID 33080110, 2020). "Apolipoprotein E knockout (ApoE−/−) mice are characterized by a marked increase in total plasma cholesterol levels and develop microvasculature lesions; making ApoE−/− mice a possible model for studying the mechanisms of hyperlipidemia and atherosclerosis in MGD and DED." (PMID 33233466, 2020). "Furthermore, the study also showed that different vascular effects, including significant mitochondrial damage in the aorta and severe progression of atherosclerosis, were seen after pulmonary exposure via intratracheal instillation to carbon black nanoparticles (CBNPs) in ApoE KO mice." (PMID 33022979, 2020). "Dysregulation of EPCs in ApoE KO mice could contribute to the development of atherosclerosis." (PMID 33022979, 2020). "To address the contribution of mTrib1 in early atherosclerosis, we first transplanted bone marrow cells from the Trib1mKO and Trib1mTg mice and their respective controls (i.e., non-CRE, floxed KO, and Tg alleles) into 12- to 13-week-old lethally irradiated male ApoE−/− mice." (PMID 31692955, 2019). "To investigate if immune responses against collagen type IV could contribute to vascular injury affecting the development of atherosclerosis we immunized ApoE−/− mice with native or MDA-collagen type IV using Alum, Freund’s incomplete or Freund’s complete as adjuvants." (PMID 30979943, 2019). "In ApoE-knockout mice infused with angiotensin II to induce atherosclerosis of the coronary arteries, coinfusion of apelin-13 could activate nitric oxide and thereby attenuate atherosclerosis of these vessels, as well as prevent vascular remodeling in a vein graft model." (PMID 31492821, 2019). "In this study, we used an animal model of ApoE−/− mice to demonstrate that vanadium exposure has detrimental effects on increasing plasma ROS and atherosclerotic cytokine IL-6 and consequently promotes the synthetic phenotype in VSMCs, which leads to atherosclerosis." (PMID 31817202, 2019). "Moreover, atherosclerosis in ApoE−/− mice is also unaffected by genetic disruption of CD8a." (PMID 31653058, 2019). "Although we were able to evaluate the relevance of MR targeting with 68Ga-NOTA-anti-MMR Nb in ApoE-KO mouse model of atherosclerosis, whether 68Ga-NOTA-anti-MMR Nb also accumulates in complex human atherosclerotic plaques needs to be validated in future studies." (PMID 30666513, 2019). "However, in subsequent studies, deletion of both SR-A1 and CD36 in apoE-deficient mice did not reduce atherosclerosis, suggesting the existence of alternative mechanisms of lipid uptake." (PMID 31717832, 2019). "Recently, it was reported that apoE functions as a checkpoint in controlling the resolution of inflammation by interacting with C1q in the complement activation pathway and subsequently reducing C5 and the inflammatory burden in atherosclerosis and Alzheimer disease." (PMID 31779116, 2019). "Therefore, the ApoE−/− mouse model may be more reflective of advanced atherosclerosis, suggesting that miR-155 may have stage-specific effects during atherosclerotic lesion development." (PMID 31139076, 2019). "In addition, suppressed cell death of dopaminergic neurons in a Parkinson’s disease animal model, prevention of atherosclerosis in an apolipoprotein E knockout (apoE KO) mouse, and suppressed mild cognitive impairment in a dementia animal model provide supporting evidence for in vivo effects." (PMID 30669692, 2019). "Previous studies indicated that ox-LDL-induced LOX-1 activation could be inhibited by miR-590-5p, and miR-590-5p agomir effectively prevented the development of atherosclerosis in ApoE−/− mice through attenuating lipid accumulation and proinflammatory cytokine secretion." (PMID 31354796, 2019).